ADAMTS13 (ADAM metallopeptidase with thrombospondin type 1 motif 13)
Diseases named in the same sentence as ADAMTS13 in open-access papers (continued):
Sharing a sentence is not in itself a finding about the gene and the disease.
cancer (32 papers, 2005 to 2025). A tumor composed of atypical neoplastic, often pleomorphic cells that invade other tissues. "Given its established role in regulating thrombotic events, ADAMTS13 has gained increasing attention in cancer research, particularly in PDAC, where cancer‐associated thrombosis is a common and severe complication." (PMID 41211185, 2025). "Multivariate logistic regression revealed two independent risk factors related to DVT in cancer patients undergoing chemotherapy: vWF:Ag and ADAMTS-13." (PMID 33292287, 2020). "The objective of this study was to investigate the roles of sP-selectin, vWF, and ADAMTS-13 as risk factors for the first episode of DVT in cancer patients undergoing chemotherapy." (PMID 33292287, 2020). "A vWF:Ag level above the 75th percentile was associated with a 3.8-fold increased risk of developing DVT, and an ADAMTS-13 level below the 25th percentile was associated with an approximately 2.7-fold increased risk of developing DVT in cancer patients after chemotherapy." (PMID 33292287, 2020). "In conclusion, in this study we could demonstrate that levels of VWF antigen and ADAMTS‐13/VWF were strongly associated with the risk of VTE in cancer patients." (PMID 31294335, 2019). "In our patient cohort we could not find any significant association in univariate competing risk analysis of only ADAMTS‐13 activity with VTE in cancer patients." (PMID 31294335, 2019). "However, they found the addition of ADAMTS‐13 to have added predictive value in risk assessment scores for cancer‐associated VTE." (PMID 31294335, 2019). "Numerous reports of various malignancy-associated changes in VWF and ADAMTS13 levels have inspired this current review into exploring these documented changes and potential associations with bleeding and thrombotic phenomena as well as possible links to cancer metastasis and prognosis." (PMID 35327035, 2022). "Therefore, it may be hypothesized that ADAMTS‐13 does influence the predictive potential of the ratio for cancer‐associated VTE, particularly concerning the stratification of low‐risk patients." (PMID 31294335, 2019). "When all cancer types were examined, ADAMTS13 expression was significantly altered in all cancer types, except bladder and renal PA." (PMID 40699668, 2025). "Beyond its established function in thrombotic regulation, the role of ADAMTS13 in cancer progression, particularly in PDAC, remains poorly understood." (PMID 41211185, 2025). "Together, these results demonstrate for the first time a direct role for ADAMTS13 in modulating tumor angiogenesis in human cancer." (PMID 41211185, 2025). "ADAMTS13 activity and VWf multimers are generally normal in most cancer-associated TMA (the median value of ADAMTS13 activity is 50% in those with cancer-associated TMA)." (PMID 40217615, 2025). "In cancer patients, a significant reduction in ADAMTS13 levels and a corresponding increase in VWF levels is observed." (PMID 39201740, 2024). "Without ADAMTS13 to cleave long VWF strings, the number of metastatic foci can significantly increase in ADAMTS13-deficient mice, suggesting these tethered VWF strings assist cancer cell adhesion on EC." (PMID 39282473, 2024). "We further conducted an analysis of the functional pathway correlations of ADAMTS13 with cancer development in CRC samples." (PMID 37691826, 2023). "Another emerging concept is utilizing VWF and ADAMTS13 as predictive and prognostic biomarkers of cancer, given their altered levels in certain malignancies, as discussed in the previous section." (PMID 35327035, 2022). "Along with ADAMTS13, VWF in excess or in deficiency can lead to cancer-associated thrombosis or bleeding." (PMID 35327035, 2022). "Both VWF and ADAMTS13 have been explored as potential biomarkers of cancer to aid in the early detection of colon cancer and HCC." (PMID 35327035, 2022).
cancer (continued). "Consistent with this, there are reports of lower levels of ADAMTS13 in patients with disseminated and advanced stage cancer compared to a more localized disease." (PMID 35327035, 2022). "A better understanding of the role VWF and ADAMTS13 play in the promotion and inhibition of cancer and its metastasis will help direct further translational studies to aid with the development of novel cancer prognostic tools and treatment modalities." (PMID 35327035, 2022). "HCC, another frequently surveilled cancer in at risk populations, was shown to be associated with a high VWF antigen to ADAMTS13 activity ratio in cirrhotic patients." (PMID 35327035, 2022). "Collectively, the evidence for VWF as a robust cancer biomarker, either alone or in combination with other markers, such as ADAMTS13, at present remain inconclusive." (PMID 35327035, 2022). "Previous studies have shown that the activity and level of ADAMTS-13 are slightly lower in cancer patients than in healthy controls." (PMID 33292287, 2020). "The dynamics of ADAMTS-13 can differentiate cancer patients who will develop DVT with a further reduction in ADAMTS-13 during chemotherapy, creating a negative delta value." (PMID 33292287, 2020). "With increasing cancer stage, both sP-selectin and vWF:Ag levels were increased, whereas ADAMTS-13 levels were decreased at the time of inclusion." (PMID 33292287, 2020). "The principal strength of our study, however, lies in the large number of diverse cancer patients studied for ADAMTS‐13 and VWF and in its long follow‐up period." (PMID 31294335, 2019). "For example, miRNAs such as MIR-181, MIR-30b, and MIR-200b as well as specific gene loci such as ADAMTS13, NOTCH4 and PIGN have been linked to many cancers, including EEC, and should be evaluated in vitro in the future." (PMID 30857319, 2019). "In the present cancer patient cohort a clear association between elevated levels of VWF and decreased levels of the ADAMTS‐13/VWF ratio and occurrence of VTE was found." (PMID 31294335, 2019). "Another study assessed the activity of ADAMTS13 in plasmas of patients with malignant tumors of various origins such as colon, blood, breast etc.." (PMID 24213506, 2012). "One study analyzed the multimeric state of vWF and ADAMTS13 metalloproteinase activity on vWF in a wide range of cancers to understand the role of vWF and ADAMTS13 in dissemination and invasiveness of cancer." (PMID 24213506, 2012). "Impaired von Willebrand factor cleaving activity of ADAMTS-13 was also demonstrated in patients with metastasizing malignant tumors." (PMID 22206706, 2011). "The majority of cancer patients had ADAMTS13 levels of more than 20%." (PMID 40217615, 2025). "A better understanding of the role that VWF and ADAMTS13 play in the promotion and inhibition of cancer and its metastasis will help to direct further translational studies to aid with the development of novel cancer prognostic tools and treatment modalities." (PMID 35327035, 2022). "High VWF levels were significantly associated with the risk of developing VTE in cancer patients, whereas ADAMTS‐13 was not." (PMID 31294335, 2019). "A stage‐dependent increase in VWF and/or respective decrease in ADAMTS‐13 could indirectly imply the correlation with worse survival of cancer patients." (PMID 31294335, 2019). "As the flat, overlapping curves show, ADAMTS‐13 did not have a statistically relevant association with probability of VTE in cancer patients." (PMID 31294335, 2019). "Lack of ADAMTS13’s catalytic activity in cleaving vWF was associated with progression of various cancers." (PMID 24213506, 2012). "Thus, further studies are required to clarify the relationship between catalytic activity of ADAMTS13 and cancer stages." (PMID 24213506, 2012).
cancer (continued). "Since the relation in the size of UL-vWF multimers via ADAMTS-13 is a relevant mechanism of thrombosis in cancer patients, reduced ADAMTS-13 levels as well as high plasma vWF:Ag levels, causing a high vWF:Ag/ADAMTS-13 ratio, may serve as independent predictive factors." (PMID 33292287, 2020). "While there is compelling evidence of localized tumor‐promoting effects, such as increased migration and invasion, we also observed alterations in potential downstream factors of ADAMTS13, such as MMP9, that have multifaceted functions in human cancers." (PMID 41211185, 2025). "Based on the detection of severe ADAMTS13 deficiency, 35 patients (81%) were diagnosed with acquired TTP, whereas the remaining 8 patients were ultimately diagnosed with complement-mediated HUS (n = 3), TMA secondary to cancer (n = 3) or TMA of unknown etiology (n = 2)." (PMID 35739601, 2022). "Low ADAMTS‐13 (a disintegrin‐like and metalloproteinase with thrombospondin type 1 motif 13) and increased von Willebrand Factor (VWF) levels in cancer patients have been described numerously." (PMID 31294335, 2019). "The aim of this investigation was to study the potential predictive value of ADAMTS‐13, VWF and their interrelationship for development of VTE in cancer patients and the correlation of values with survival probability in a large patient cohort." (PMID 31294335, 2019). "Cancer patients have been shown to have higher VWF levels and lower ADAMTS‐13 levels than the general population, often also in a stage‐dependent intensity." (PMID 31294335, 2019). "In multivariable Cox regression analysis adjusting for possible confounding factors, both ADAMTS‐13 and VWF alone and in combination remained statistically significant for survival probability in cancer patients (both P < 0.05 and P < 0.001, respectively)." (PMID 31294335, 2019). "This is in accordance with the literature, which frequently describes lower ADAMTS‐13 and higher VWF levels in cancer patients, often also in a stage‐dependent intensity." (PMID 31294335, 2019). "However, these discrepancies may be explained by the fact that we excluded from the analysis TMA associated with other conditions (transplantation, cancer and chemotherapy or HIV infection), which are usually associated with detectable ADAMTS13 activity and a very poor prognosis." (PMID 20436664, 2010). "The main barrier to utilizing VWF as a potential target for cancer therapy is the relative infancy of our understanding of how VWF and ADAMTS13 mechanistically affect malignancy and metastasis, and the heterogeneity and inconsistencies reported in the literature." (PMID 35327035, 2022). "The vWF:Ag/ADAMTS-13 ratio was significantly higher in cancer patients with DVT than in those without (+ 4.12 vs. + 1.40, p = 0.001)." (PMID 33292287, 2020). "Plasma samples from patients with advanced stage of malignancy from different cancers showed reduced ADAMTS13 activity (6–30% activity of the normal plasma)." (PMID 24213506, 2012). "Measuring ADAMTS13 in cancer may not be helpful, as it could range from undetectable to normal levels, with most patients presenting an adequate level." (PMID 39997356, 2025). "The predictive values of the platelet count, lactate dehydrogenase, absent active cancer, schistocytes, mean corpuscular volume, international normalized ratio, creatinine (PLASMIC) score were utilized to predict severe acquired ADAMTS13 deficiency; a score of six was obtained." (PMID 39185293, 2024). "Results of the cohort of Pépin et al21 were similar, as cancer patients with VTE had mean ADAMTS‐13/VWF values of 0.36 (IQR 0.22‐0.49) and cancer patients without VTE had 0.44 (IQR 0.28‐0.57)." (PMID 31294335, 2019).
cardiovascular disease (25 papers, 2008 to 2025). "Fibrinogen, vWF, and ADAMTS13 play important roles in both coagulation and inflammation, and have been reported as independent risk factors for cardiovascular disease." (PMID 34559294, 2022). "This study aimed to determine the causal effect of ADAMTS13 level and activity on common cardiovascular diseases by conducting a two-sample MR analysis." (PMID 34276770, 2021). "We applied a two-sample Mendelian randomization approach incorporating genome-wide association summary statistics to verify the causal association between ADAMTS13 level, as well as activity and cardiovascular diseases." (PMID 34276770, 2021). "The combination of a low ADAMTS13 activity with a high concentration of VWF is likely to be prothrombotic with an increased risk of cardiovascular diseases and death." (PMID 34134634, 2021). "Our study verified the causal relationship between ADAMTS13 level and activity and six types of cardiovascular disease using the MR method." (PMID 34276770, 2021). "Second, we used high statistical powers to detect the causal association of risk factors and ADAMTS13 with cardiovascular disease by using the MR approach." (PMID 34276770, 2021). "Both in vitro and animal studies have shown that ADAMTS13 has antithrombotic properties, and reduced ADAMTS13 level and activity can increase the risk of cardiovascular disease." (PMID 34276770, 2021). "Low ADAMTS13 activity is associated with an increased risk of cardiovascular disease, which is generally attributed to its proteolytic effects on Von Willebrand factor (VWF)." (PMID 29615758, 2018). "This study aims to estimate whether the level and activity of ADAMTS13 are causally associated with common cardiovascular diseases." (PMID 34276770, 2021). "We suggest ADAMTS13 deficiency could be a novel risk factor for cardiovascular diseases in chronic HD patients." (PMID 34819564, 2021). "Furthermore, there is increasing evidence suggesting that even a moderate decrease in ADAMTS‐13 activity can also predispose to cardiovascular disease." (PMID 29108103, 2018). "In the case–control study by Bongers and colleagues, it was shown that patients with cardiovascular disease had lower levels of ADAMTS13 activity in comparison to healthy individuals." (PMID 40217918, 2025). "The role of ADAMTS13 genetic variants in the prediction of the long-term cardiovascular outcomes of allo-HCT recipients should be further evaluated, given the increased cardiovascular disease burden that they experience." (PMID 40724958, 2025). "Both markers have been related to cardiovascular disease (CVD).We aimed to investigate the influence of ADAMTS13 single nucleotidepolymorphisms (SNPs) on levels of ADAMTS13 and VWF, and CVD." (PMID 36474435, 2022). "Identifying the role of ADAMTS13 in cardiovascular diseases is pivotal for prevention as well as early intervention in patients with latent cardiovascular diseases." (PMID 34276770, 2021). "Our results help to identify the role of ADAMTS13, including the level and activity, in cardiovascular disease via a genetic approach." (PMID 34276770, 2021). "The correlation of ADAMTS13 with cardiovascular diseases has been gradually recognized, although its role in the pathogenesis of cardiovascular diseases is inconclusive." (PMID 34276770, 2021). "Many observational studies have reported the relationship between ADAMTS13 and some cardiovascular diseases but have drawn different conclusions, likely attributed to confounding factors lacking adjustment." (PMID 34276770, 2021). "One study has shown that young patients with low ADAMTS13 levels are five times more likely to develop cardiovascular disease than those with normal ADAMTS13 levels." (PMID 34276770, 2021). "At present, less attention has been paid to the correlation between ADAMTS13 and other cardiovascular diseases such as AF, VTE, and HF." (PMID 34276770, 2021).
cardiovascular disease (continued). "Long term prospective trials at large scale are required to explore the predictive role of VWF and ADAMTS13 in cardiovascular diseases." (PMID 32095288, 2020). "Further insights into the roles of the ADAMTS‐13–VWF axis in cardiovascular diseases, and the potential of rADAMTS‐13 as a therapeutic agent, have been obtained with experimental models, some of which are summarized below." (PMID 29108103, 2018). "The dynamics of both VWF and ADAMTS‐13 are of potential importance in cardiovascular diseases and their management." (PMID 29108103, 2018). "The activation of vWF and its counterbalance by ADAMTS-13, the vWF-cleaving protease, might contribute to complications of cardiovascular diseases." (PMID 33096906, 2020). "The level of ADAMTS-13 in the blood may thus influence cardiovascular disease, especially in some population subgroups." (PMID 24453831, 2013). "VWF has effects that are largely unaffected by other cardiovascular disease risk factors, unlike ADAMTS-13, which appears to have effects that are masked by the coexistence of other risk factors." (PMID 18194418, 2008). "Impaired function of ADAMTS13 might contribute to the development of cardiovascular disease." (PMID 40217918, 2025). "Therefore, a study focusing on ADAMTS13 and cardiovascular diseases in HD patients is expecting." (PMID 34819564, 2021). "The imbalance levels of ADAMTS13 and VWF in circulation will lead to the occurrence of cardiovascular disease." (PMID 35155621, 2021). "Furthermore, because of the lack of direct evidence, it remains unclear whether ADAMTS13 is a causal independent risk factor of cardiovascular disease." (PMID 34276770, 2021). "Researchers have expressed concern about whether ADAMTS13 and VWF had a co-effect on cardiovascular disease." (PMID 34276770, 2021). "Nevertheless, the limited evidence of direct correlation between ADAMTS13 and cardiovascular diseases is due to the lack of comparability of interdisciplinary research, weak statistical correlation, and the inability to adjust for confounding factors." (PMID 34276770, 2021). "Patients who undergoing hemodialysis (HD) suffered from higher prevalence of CHD and stoke, however, the impacts of ADAMTS13 on cardiovascular diseases of HD patients are not clearly defined." (PMID 34819564, 2021).